CD4 (CD4 molecule)
Diseases named in the same sentence as CD4 in open-access papers (continued):
Sharing a sentence is not in itself a finding about the gene and the disease.
depression (continued). "In another study in Rwanda among HIV positive women (with study population overlap) depression (p < 0.001), but not PTSD (p = 0.60), was associated with CD4 count." (PMID 29881448, 2018). "However, it is difficult to parse the temporal relationship between CD4 cell counts, ART treatment and depression." (PMID 29590151, 2018). "Participants who had a lower CD4 cell count at the start of ART or who received ART at the clinic without HCT services were more likely to suffer from depression." (PMID 30562949, 2018). "Among patients not taking ART, those with a low CD4 cell count (≤ 350 cells/mm3) reported more depressive disorders than those with a higher CD4 cell count (7.1% vs. 0.9%, p = 0.029)." (PMID 29590151, 2018). "Secondary aims of the trial are to examine the effect of the vitamin D3 regimen on CD4 T cell reconstitution, incidence of non-TB comorbidities, body mass index (BMI), depression and anxiety, physical activity, bone health, and immunologic biomarkers." (PMID 28183335, 2017). "The presence of depression symptoms correlated with non-adherence to ART during antibiotic treatment (r = 0.53, p = 0.04), and was associated with lower CD4 cell counts (p = 0.04) and longer non-adherent periods (p = 0.04)." (PMID 28141867, 2017). "This study showed that having 2 years and above duration on ART, depression symptoms, history of ART adverse effect, substance use, living with parents, <350 cells/mm3 CD4 count and low dietary diversity in the household as determinant factors for non-adherence to ART." (PMID 28331527, 2017). "In contrast, there was an increase in IL10 production by CD4 T cells in hip fracture patients with new onset depression compared to hip fracture patients without depression (p = .04) and healthy controls (p = .02)." (PMID 26112234, 2016). "CD4 (T helper/inducer cells) significantly differ between controls and ADHD, mental retardation, and epilepsy; between depression and ADHD, mental retardation, and epilepsy; between migraine and ADHD and mental retardation; and between cerebrovascular insufficiency, ADHD, and mental retardation." (PMID 27190492, 2016). "A positive relationship was found between activity limitations and depression symptoms, adherence, and worse health outcomes, while none was found for BMI or CD4 count." (PMID 26625001, 2015). "The focus of this analysis is to explain the gap in the mean y’s, for which the raw differential of 61.94 in CD4 counts and a raw differential of 1.80 in depression symptoms occurs among the two groups, Non-Hispanics and Hispanics." (PMID 25560348, 2014). "After analysis and comparison using three different statistical methods, B2M and RPLP0 were identified as the most suitable HKGs for gene expression studies in uncultured CD4+ T cells of asthmatics with or without depression." (PMID 23110234, 2012). "Most recent CD4 counts were similar among patients with and without depression (433.4 vs. 453.5 cells/mm3, P = 0.384)." (PMID 19265529, 2009). "After grouping depression patients according to length of hospital stay, except for CD4+ Tn MM, CD4+ Tcm MM in the routine-term hospitalization group, there was no significant improvement in MM of other CD4+ T subpopulations before and after treatment." (PMID 40756310, 2025). "However, pre-treated rats with hesperidin could significantly increase the population of CD4+CD25+Foxp3+Treg in OVA-induced bronchial asthma and depression." (PMID 37950769, 2024). "Inflammatory depression, a treatment-resistant or non-responsive subtype of depression, may be related to the interaction between the gut microbiota and interleukin-17-producing CD4+ T cells (Th17 cells)." (PMID 39655201, 2024). "A decrease in CD4 + cell count may account for an additional immunological impact of depression independent of ART adherence, which may explain the discrepancy in results across studies." (PMID 38168236, 2023).
depression (continued). "Subgroup analysis showed that LC3B protein expression of blood CD3+CD4+ T helper cell was further decreased in sleep-disordered breathing (SDB) patients with depression as compared with that in those without depression (1.18 ± 0.43 versus 1.43 ± 0.48, adjusted p = 0.01)." (PMID 36805797, 2023). "This suggests that depression may lead to sleep disturbances and abnormal cell-mediated immunity and inflammation, especially the percentage of CD3+CD8+ T cells, CD3+ T cells, the CD4+/CD8+ T-cell ratio and SII in patients with CHD." (PMID 36688007, 2022). "In support of this concept of heterogeneity in MDD, a recent study found distinct immunologic profiles for inflamed and non-inflamed depression, with the inflamed group characterized by increased levels of circulating neutrophils, monocytes, CD4+ T cells along with elevated IL-6 and CRP." (PMID 35332134, 2022). "PLHIV with and without depression both experienced a decrease in CD4 count during the study period (11.6 cells/mm3 and 51.4 cells/mm3 respectively), however this decline was even greater among depressed, with a difference of 39.8 cells/mm3 (beta=−39.8, 95% CI=−57.8, −21.8)." (PMID 33490927, 2021). "However, our results do not support a maintained and chronic activation of CD4+ T lymphocytes in cases of depression." (PMID 33808804, 2021). "Attempts were made in all the studies except in one to control for possible confounding factors such as non-age demographic factors, HIV biomarkers (e.g. nadir CD4), comorbidities, substance use and depression, and factors which are significantly different between HIV + and HIV- participants." (PMID 33025390, 2021). "In Kaplan-Meier analysis participants with depression at baseline, HSV-2 coinfection at baseline, set point HIV VL ≥5 log10 copies/mL (vs. < 5), and persistence of symptoms ≥ 2 weeks (vs. < 2 weeks) reached the endpoint of a CD4+ T cell count < 350/μL at a significantly faster rate." (PMID 34367176, 2021). "UMHC could have severe negative consequences, for instance, depression has been associated to less adherence to ART resulting in virological failure, decline in lymphocyte CD4+ recount, resistance to antiretroviral drugs and increase in mortality." (PMID 32751759, 2020). "TNFα concentrations were not correlated with the severity of anxiety (Spearman r = 0.15; p = 0.27), depression (Spearman r = 0.18, p = 0.19) or somatization (Spearman r = 0.14; p = 0.28), suggesting that psychological symptoms and CD4+ T-cell stimulated cytokines were not related." (PMID 30842618, 2019). "Third, as we did not screen for clinical depression among participants, we are not able to specify how it may affect the results, particularly with regard to NA and CD4 count." (PMID 30097904, 2019). "Among patients not taking ART, the prevalence of depression was higher for those with CD4 counts ≤ 350 cells/mm3 compared to those with higher CD4 counts; the confidence limits and p-value for this result do not agree due to the approximation used to pool the estimates across the imputed datasets." (PMID 29590151, 2018). "Participants with cryptococcal meningitis had the lowest median CD4 count (17 cells/μL, IQR: 7–79), the lowest median Karnofsky score (60, IQR: 50–70), the highest proportion of participants with IHDS < =10 (92%), and the highest median scores for depression (CES-D: 23, IQR: 16–30)." (PMID 28606065, 2017). "Individuals with a history of unipolar depression (whether with or without clinically relevant symptoms of depression) exhibited shorter telomeres in the three analyzed leukocyte subsets (CD4+ T helper cells, CD8+ cytotoxic T cells, and CD20+ B cells)." (PMID 24996455, 2014). "Since CD4 cell count has been used to measure disease progression in HIV, this, together with the findings of the present study, suggests further research is needed in low-income countries to assess the potential relationship of depression, immunity, and HIV disease progression in PLHA on ART." (PMID 24852246, 2014).
depression (continued). "Women showed a greater CD4 cell reduction than men in our study unlike in a study by Wichmann where men suffered longer lasting depression of CD4 than women of about 5 days while the depression in the women the CD4 depression lasted only 2 days." (PMID 23442732, 2013). "Therefore, CD4+CD25+ Treg cells may provide a promising strategy for the development of CD4+CD25+ Treg cell-based therapies that will alleviate stress induced disorders, including depression." (PMID 22860054, 2012). "However, the role of CD4+CD25+ Treg cells in major depression, which also exhibits immune imbalance, has not yet been explored." (PMID 22860054, 2012). "Depression and current CD4 count did not affect performance on any of the cognitive measures." (PMID 20406460, 2010). "The post-chemotherapy increase in CD4 numbers followed the same kinetics as the other subsets with no extended depression as one might expect following fludarabine treatment." (PMID 17868452, 2007). "Notably, a novel joint index based on the CD4+/CD8+ T cell ratio, albumin concentration, and M% was developed in the present study, and it showed superior sensitivity and specificity to discriminate the severity of the depressive disorder in comparison to the individual significant factors." (PMID 35395781, 2022). "CD4+ cell counts were measured during acute illness in the case-control study; the degree of immunosuppression may not be accurately represented because CD4+ cell count depression can occur during acute illness." (PMID 29045699, 2018). "Another shortcoming in this study is the lack of biological markers (e.g., CD4 cell count and HIV load) to predict mothers that were likely to develop pregnancy complications, or to determine the association of these biologic markers with alcohol use, drug abuse, or depression." (PMID 29507814, 2018). "We tested hypotheses that exposure to IPV, non-partner rape, hunger, pregnancy, depression and substance abuse predicted change in CD4+ and CD8+ T-cell count in a dataset of 103 HIV infected young women aged 15-26 enrolled in a cluster randomised controlled trial." (PMID 25816336, 2015). "Lack of HIV treatment in prisoners with CD4 lymphocyte count < 350/mm3 was due to medication refusal (69.2 %), ongoing medical assessment (23.1 %) and other reasons including fear of side effects, cultural or ethnic beliefs, depression or delusional state (7.7 %)." (PMID 26653247, 2015). "The few studies that have been conducted in sub-Saharan Africa suggest the following risk factors for depression in PLWHA: female gender, older age, unemployment, negative life events, childhood trauma, impaired function, poor social support, poor quality of life, and low CD4 counts." (PMID 26503291, 2015). "Anxiety and depression markedly influence the immune function of cancer patients, with affected individuals showing notably reduced levels of CD3 and CD4 cells compared to patients without these conditions, while CD8 cell levels tend to be elevated." (PMID 41446305, 2025). "Most HIV disease outcomes (CD4, viral suppression, WHO stage, medication adherence) were not significantly different in those with and without depression at baseline." (PMID 37227670, 2023). "CD4 and CD8 were detected to be lower among college students with anxiety and depression than in those without symptoms, indicating lower concentrations of immune parameters are associated with depression and anxiety symptoms among healthy adults." (PMID 36339832, 2022). "In line with this, our study found that CD3, CD4, and CD8 levels were lower in patients with depression and/or anxiety than in those without symptoms, possibly involving in change of psychoneuroimmunology." (PMID 36339832, 2022). "Several authors have observed a positive association between CD4 count and physical and emotional components of quality of life in this patient group, and, particularly, a negative link between CD4 count and HIV-related depression." (PMID 30097904, 2019).
depression (continued). "Given the well-documented links between CD4 levels and multi-morbidity, as well as ART non-adherence and depression in older HIV populations, special efforts must address these disparities among older HIV-positive Hispanics." (PMID 25560348, 2014). "PHD was significantly associated with increasing stress scores and psychosocial impairment but not with age, BMI, CD4 count, use of HAART, or a diagnosis of depression or alcohol dependence." (PMID 23641703, 2013). "We found that nonadherence to PCP prophylaxis was associated with illicit drug use, mental health issues including depression, nonadherence to prescribed ART, and low CD4 cell count." (PMID 19319199, 2009). "It is also possible that the newly created naïve CD4+ and CD8+T cells are not involved in limbic system support, but strengthen the defense against microbes which might be involved in inducing depression." (PMID 39867848, 2025). "AHR or RORγt genetic impairment in CD4+T cells does not eliminate depression vulnerability in UCRS mice, whereas neutralization of RORα and RORγt may prevent depression in UCRS rats." (PMID 39655201, 2024). "However, the effects of monocytes on the polarization of CD4 + T cells to TH2 cells and TH17 cells were comparable between UC patients with and without symptoms of anxiety and depression." (PMID 36906523, 2023). "The counts of CD3, CD4, CD8, and lymphocytes decreased, whereas those of neutrophils, platelets, and peripheral blood cells and their derived indices increased among TB patients with depression or anxiety in comparison with those without symptoms (p < 0.05)." (PMID 36339832, 2022). "At baseline, education, prior psychiatric illness and co-existing moderate depression (PHQ-9 > 9), but not HIV-specific parameters (HIV-1 RNA level and CD4+ T-lymphocytes nadir) or co-infections (syphilis and HCV), tended to be independently associated with poor IHDS performance." (PMID 30760220, 2019). "While it follows that untreated depression could affect a patient’s choice not to initiate ART, which would, in turn, lead to suppressed CD4 cell levels, the research is somewhat mixed." (PMID 29590151, 2018).
gastric cancer (275 papers, 2003 to 2026). A primary or metastatic malignant neoplasm involving the stomach. "WDR72 was negatively correlated with activated memory CD4+ T cells and positively associated with resting CD4 memory T cells, consistent with findings in gastric cancer." (PMID 41332473, 2025). "HF induces dramatic CD4+ T cell activation, which is associated with increased gastric cancer risk in humans." (PMID 38682907, 2024). "This study, for the first time, explored the association between CD3+/CD4+ cell–myosteatosis and the prognosis of patients who underwent surgery for gastric cancer." (PMID 38894548, 2024). "One study suggested that patients with a higher proportion of CD4+CD25+ Treg cells was associated with a poorer prognosis in gastric cancer." (PMID 39275896, 2024). "For example, activated CD4+ T cells in gastric cancer were associated with the worse overall and progression-free survival in gastric cancer." (PMID 38801557, 2024). "Potential mechanisms underlying the predictive capabilities of CD3+/CD4+ cell binding myosteatosis in gastric cancer surgery outcomes were considered." (PMID 38894548, 2024). "CD8 + T cells were associated with improved OS in patients with gastric cancer, while high infiltration of CD4 + T cells was correlated with worse OS." (PMID 39088070, 2024). "T cells CD4 memory resting have been found to have lower expression in tumor tissues and high-risk group in gastric cancer specimens." (PMID 39575189, 2024). "Recently, Ning and colleagues identified that CD4+ memory T cell-based gene risk score is associated with the prognosis of patients with gastric cancer." (PMID 36878969, 2023). "The prognosis of breast cancer, gastric cancer, lung adenocarcinoma, and pancreatic cancer is strongly linked to CD4+ memory T cells." (PMID 37781029, 2023). "High CD4 memory activated T cells was significantly associated with better overall survival in gastric cancer." (PMID 37033978, 2023). "The high percentages of circulating PD-1+CD8+ T and PD-1+CD8+ Tm as well as PD-1+CD8+T/PD-1+CD4+T cell ratio at the baseline were significantly associated with good prognoses in advanced gastric cancer patients treated with ICI therapy plus chemotherapy." (PMID 37974194, 2023). "Meanwhile, substantial abundance of CD4+ memory resting T cells is associated with unfavorable prognosis in gastric cancer." (PMID 37753093, 2023). "Studies have shown that CD4 memory T cells are associated with better survival in patients with gastric cancer." (PMID 37274740, 2023). "The TIMER algorithm revealed a greater presence of CD4 T cells, neutrophils, macrophages, and myeloid dendritic cells in high-risk gastric cancer." (PMID 37711621, 2023). "In gastric cancer, systemic inflammation is associated with the density of CD4 + lymphocytes in the tumor microenvironment." (PMID 35964056, 2022). "The high abundance of tumor-associated lymphocytes, including CD8+ T cell, CD4+ T cell, and NK cell, plays a positive impact on prognosis of gastric cancer by dissolving tumor cells directly." (PMID 34262565, 2021). "In gastric cancer, patients with low risk scores had increased number of activated CD4 memory cells and had superior prognosis." (PMID 34277706, 2021). "T cells CD4 memory activated, T cells CD4 memory resting, Macrophages M2, and Mast cells activated were found associated with gastric cancer survival risk significantly with p-value <0.05." (PMID 33442396, 2021). "We identified 105 genes that were significantly associated with the prognosis of gastric cancer that were defined as CD4+ memory cell-related genes (CD4+ MTRGs)." (PMID 33816214, 2020). "In this setting increased CD4+FoxP3+ expressing T cells following PD-1 inhibition are associated with hyperprogression in patients with gastric cancer." (PMID 32183719, 2020).